IL17RA (interleukin 17 receptor A)
Diseases named in the same sentence as IL17RA in open-access papers (continued):
Sharing a sentence is not in itself a finding about the gene and the disease.
infection (90 papers, 2010 to 2026). The state of being infected such as from the introduction of a foreign agent such as serum, vaccine, antigenic substance or organism. "Loss of B cell-intrinsic IL-17RA signaling during MHV68 infection resulted in approximately 1 million fewer peritoneal cells on average." (PMID 41335125, 2025). "We found that loss of B cell-intrinsic IL-17RA signaling in the context of MHV68 infection led to attenuated MHV68 latency and MHV68-driven germinal center response in the spleen." (PMID 41335125, 2025). "Loss of B cell-intrinsic IL-17RA signaling during MHV68 infection led to a reduction in the number of CD11b+ macrophages as well as the frequency and number of B-1a and B-1b." (PMID 41335125, 2025). "Loss of B cell-intrinsic IL-17RA signaling during MHV68 infection led to a reduction in overall spleen size following infection." (PMID 41335125, 2025). "Loss of IL-17RA signaling in B cells during MHV68 infection also led to significant attenuation in viral latency and reactivation in the peritoneal cavity." (PMID 41335125, 2025). "Loss of IL-17RA signaling in B cells during MHV68 infection only impacted viral latency in B cells with viral latency in non-B cells being identical in the presence or absence of IL-17RA signaling in B cells." (PMID 41335125, 2025). "Loss of IL-17RA signaling in B cells during MHV68 infection resulted in a loss of around 50%–60% of the plasma cells and B-1a and B-1b cells in the spleen." (PMID 41335125, 2025). "Using mice deficient in IL-17RA, it has been shown that this cytokine is required for host protection against the infection caused by T. cruzi in the acute phase of the disease." (PMID 39119291, 2024). "In this model, loss of IL-17RA increased 2-week infection rates from 25% in wild-type (WT) animals to 100% in IL-17RA-/- mice and increased overall bacterial loads." (PMID 39015565, 2024). "Our results suggest that DETCs are also one of the subsets of γδ T cells that contribute to anti-staph immune responses, since IL17RA KO mice depleted of DETCs showed enhanced susceptibility to infection." (PMID 37691956, 2023). "Specifically, the infection of C. albicans caused the activation of the IL-17A/IL-17RA signaling pathway in OC cells." (PMID 37067414, 2023). "When challenged with Candida, the susceptibility to infection of Il17ra−/− and Il17r conditional deletion (Il17raΔK13) mice was similar and associated with induction of the AMP, murine β-defensin-3." (PMID 35979535, 2022). "There was a trend towards decreased weight loss in the Il17ra KO animals following SRL2 infection and significantly lower clinical scores in this group compared to the infected wild type animals." (PMID 29813133, 2018). "The increased mortality in the IL-17RA knockout animals was associated with a significant increase in the recovered viable bacteria in blood at 48 hours after infection." (PMID 29813133, 2018). "Two months after infection the CD11b+Ly6G+ cell response was lower in the lung of IL-17RA- and IL-17RA-IL-22-deficient mice, compared to wild type mice and IL-22-deficient mice, whereas monocytic CD11b+Ly6C+ cells were decreased in IL-22-deficient mice." (PMID 27853279, 2016). "Again, IL-17C-/- and IL-17RE-/- mice demonstrated the same susceptibility to disseminated disease as WT littermate controls, while IL-17RA-/- were reproducibly more susceptible to infection." (PMID 25849644, 2015). "To address the role of the augmented IFN-γ response in the increased susceptibility of IL-17RA KO mice to T. cruzi, we evaluated the progression of the infection in mice receiving a IFN-γ blocking treatment." (PMID 22577359, 2012). "Our results using mice deficient in IL-17RA signaling show that the percentage of IL-17A+ neutrophils were decreased by approximately 47% compared to wild-type mice during infection with C. neoformans strain H99γ, which supports this conclusion." (PMID 23216912, 2012).
infection (continued). "Loss of IL-17RA signaling in B cells during MHV68 infection led to an attenuation of viral latency and reactivation and suppression of B-1 cell populations in both the spleen and peritoneal cavity, as well as a significant reduction in the MHV68-driven germinal center response in the spleen." (PMID 41335125, 2025). "Interestingly, loss of B cell-intrinsic IL-17RA expression during MHV68 infection led to a significant increase in the frequency and number of extrafollicular antibody-secreting cells." (PMID 41335125, 2025). "Loss of B cell-intrinsic IL-17RA signaling during MHV68 infection resulted in a decrease in splenomegaly, with a significant reduction in the frequency and total number of overall B cells in the spleen of infected CD19 Cre-positive mice compared to CD19 Cre-negative mice." (PMID 41335125, 2025). "Indeed, aged IL-17RA-deficient mice were shown to be more susceptible to infection upon oral gavage with Lm compared to WT mice." (PMID 35501808, 2022). "Using mCherry-Br stained with eFluor, we confirmed by flow cytometry and confocal microscopy that the higher susceptibility of IL-17RA-/- mice and asthmatic mice was correlated to a higher frequency of mCherryhigh AMs at 48 hours post-infection, compared to wild-type mice." (PMID 35771771, 2022). "Studies have shown an interaction between Orf8 and IL-17 receptor A (IL-17RA), suggesting that this interaction regulates IL-17 signaling and infection with SARS-CoV-2 virus with deletions of Orf8 associated with milder disease symptoms and low pro-inflammatory cytokine secretions." (PMID 34576690, 2021). "However, IL-17RA knockout mice showed a smaller initial weight loss and early recovery of their starting weight after infection, a significant difference from the WT animals." (PMID 27698020, 2016). "Thus, excessive infection of C. albicans may cause more IL-17A production and release, which further activates the IL-17A/IL-17RA signaling pathway in OC cells to induce macrophage infiltration." (PMID 37067414, 2023). "In addition, the deficiency of IL-6, IL-23, or IL-17 receptor A (IL-17RA) impaired the compact granuloma formation and conferred susceptibility during infection, associated with reduced tumor necrosis factor-α, IFN-γ, and inducible nitric oxide synthase enzyme expression." (PMID 28871251, 2017). "IL-17RA-signaling was required to replenish neutrophils in nasal tissue that were otherwise depleted during infection." (PMID 42085507, 2026). "Rather than driving neutrophil specific chemokine expression, IL-17RA-signaling was required to replenish neutrophils in nasal tissue that were otherwise depleted during infection." (PMID 41648219, 2026). "In summary, our findings show that B cell-intrinsic IL-17RA signaling is proviral in the context of MHV68 infection." (PMID 41335125, 2025). "The impact of B cell-intrinsic IL-17RA signaling on the peritoneal cavity during MHV68 infection was examined next." (PMID 41335125, 2025). "Analysis of macrophage‐related cytokines and chemokines found that Tnf, Il1b, Il1a, Ilrn, Il17ra, Cxcl1, Cxcl2, Ccrl2, Ccl3, Ccl4, and Ccl9 expression significantly increased over the course of infection." (PMID 41117166, 2025). "As EBV and MHV68 are B-cell-tropic viruses (7, –, 11), we set out to better understand the impact B cell-intrinsic IL-17RA signaling had on MHV68 infection." (PMID 41335125, 2025). "The mice generated in this study will provide an excellent tool to understand the significance of IL-17RA signaling in B cells in a wide range of autoimmune and infection models." (PMID 41335125, 2025). "Taken together, these data indicate that B cell-intrinsic IL-17RA signaling during MHV68 infection supports the establishment and maintenance of the virus-driven germinal center response." (PMID 41335125, 2025).
infection (continued). "In the future, studies will continue to determine the combination of cell subsets that require IL-17RA signaling to support MHV68 infection as well as investigate potential mechanisms of IL-17RA signaling that support MHV68 infection." (PMID 41335125, 2025). "In this study, we examine the role of B cell-specific IL-17RA signaling in the context of gammaherpesvirus infection, given these viruses’ reliance on B cells to establish and maintain lifelong infection." (PMID 41335125, 2025). "Upon infection with MHV68, B cell-specific IL-17RA-deficient mice had significantly attenuated viral latency and reactivation in both the spleen and peritoneal cavity compared to IL-17RA B cell-sufficient control mice." (PMID 41335125, 2025). "In sea bass brain, il17ra and il17re-like were significantly decreased at 1dpi, whereas il17rb levels were increased at all the infection times, and il17ra and il17rd did at 15 and 1 dpi, respectively." (PMID 38827125, 2024). "As both bacteria and IAV can activate IL-17RA leading to differential outcomes vis-à-vis the resolution of infection and tissue damage, the notable difference between the two is potentially the magnitude of IL-17RA activation." (PMID 38060620, 2023). "DETCs were depleted from both WT and IL17RA KO mice, and the mice were subsequently infected with bioluminescent staph and the infection followed with IVIS imaging." (PMID 37691956, 2023). "The reduced bacterial burden (NP and blood) in IL-17RA KO mice suggests that IL-17RA signaling is sufficient to promote epithelial injury in the NP, allowing Spn colonization to develop into an invasive infection during IAV." (PMID 38060620, 2023). "On the other hand, DKO mice initially started to clear the infection and on day 3 actually showed a signal that was lower than that of IL17RA KO mice and comparable to that of WT and Ets1 KO controls." (PMID 37691956, 2023). "The major findings of our study are that during IAV infection, IL-17RA is a significant regulator of neutrophilia, promotes NP inflammation, tissue pathology, and converts Spn bacterial colonization to an invasive infection." (PMID 38060620, 2023). "IL-17RA expression was also comparable between M. intracellulare-infected H1975 human lung epithelial cells (1 day after in vitro infection) and uninfected cells." (PMID 35363832, 2022). "WT mice exposed to only OPC had higher MPO production compared to infected Il17ra−/− mice, which aligns with the high fungal burden in Il17ra−/− compared to immunocompetent WT mice that clear infection by this time point." (PMID 35628751, 2022). "Infection with T. canis led to increased frequency of both eosinophils and neutrophils in IL-17RA-/- mice compared to IL-17RA-/- 0dpi." (PMID 35844540, 2022). "We found 8 VLF genes for wild-type lung conditions displaying an increase >1.0 of their TnIF in the IL-17RA-/- lung condition, meaning that these mutants have a better chance to survive or multiply (or both) upon infection of IL-17RA-/- mice." (PMID 35771771, 2022). "Sham (PBS)-infected WT mice and Il17ra-/- mice were used as controls for infection clearance, respectively." (PMID 35380879, 2022). "Flow cytometric analysis showed that liver CD11b+Gr-1+ cells also expressed IL-17RA at 4 and 6 weeks post-infection." (PMID 32611373, 2020). "We examined mRNA expression of both the IL-17RA and IL-17RE receptor subunits in columnar and basal cell enriched fractions, at baseline and following infection with HRV." (PMID 32232015, 2020). "The Il17ra KO mice showed a clear and significant survival advantage following infection with this strain, the reverse of the result following infection with the invasive TIGR4 strain." (PMID 29813133, 2018). "Numbers of neutrophils in both blood and BALF in infected animals culled at 24 hours after infection were significantly lower in the Il17ra KO animals." (PMID 29813133, 2018).
infection (continued). "As determined by the amounts of parasite DNA quantified in the spleen, we observed that T. cruzi infected IL-17RA KO mice controlled tissue parasitism similar to WT mice during the first 2 weeks of infection." (PMID 30364284, 2018). "For these experiments, mice were treated with neutralizing IL-17RA mab (M751) before and during infection with M. tuberculosis." (PMID 29338039, 2018). "Specifically, IL-17RA expression was increased and sustained in memory cells, but was transiently up-regulated in activated effector cells at early stages of infection." (PMID 30364284, 2018). "At 24 hours after infection wet/dry lung weights were significantly higher in WT animals, consistent with increased pulmonary edema in these mice compared to the Il17ra KO animals." (PMID 29813133, 2018). "WT animals became bacteremic at earlier time points following infection compared to the Il17ra KO animals." (PMID 29813133, 2018). "Using gene expression data normalized to the corresponding non-infected samples, we compared the transcriptional changes induced by infection in CD8+ T cells from IL-17RA KO mice vs. WT mice in a fold change/fold change plot." (PMID 30364284, 2018). "Epithelial cells (ECs) express the IL-17 receptor (IL-17RA/RC) and are involved in fungal clearance via production of various proinflammatory cytokines and antimicrobial peptides during infection." (PMID 29371568, 2017). "Although 71% of IL-17RA-/- mice survived the “SL” infection, they largely succumbed to re-infection." (PMID 27078879, 2016). "Following inoculation with the YH5 P. aeruginosa strain, the infection rates 2 weeks later were 25% in WT animals (5 out of 20 animals) and 100% in IL-17RA knockout mice (20 out of 20 animals), a highly significant difference (P < 0.0001, Fisher's exact test)." (PMID 27698020, 2016). "Accordingly, IL-17RE-/- and littermate control mice were infected intradermally with C. albicans hyphae (strain CAF2-1) using an infection model that previously demonstrated an essential of IL-17RA in protection from dermal candidiasis." (PMID 25849644, 2015). "We previously identified a panel of IL-17RA-dependent signature genes that are induced after exposure to C. albicans that represent the overall transcriptional response to infection." (PMID 25849644, 2015). "Most notably and unique to the H. pylori model of infection, we found that IL-17RA signaling was necessary to limit B cell infiltration to the gastric mucosa." (PMID 23533678, 2013). "Previous studies in our laboratory demonstrated that IL-17RA is required to control infection with Helicobacter pylori in the mouse model." (PMID 23533678, 2013). "In contrast, the concentrations of IL-17F, and its soluble receptor IL-17RA were the highest in infection-free controls." (PMID 22969818, 2012). "We analyzed levels of pro-inflammatory IL-17 members (IL-17A, IL-17B and IL-17F) as well as their soluble common receptors (IL-17RA and IL-17RB) in clinically staged AE patients, that is, cured, stable, and progressive AE, and in infection-free controls." (PMID 22969818, 2012). "During the course of the infection, both group of mice presented similar cell numbers in secondary lymphoid organs, but infected IL-17RA KO mice showed a reduced number of infiltrating cells in liver." (PMID 22577359, 2012). "At day 20 post-infection, plasma levels of both cytokines were significantly higher in IL-17RA KO mice than in WT mice." (PMID 22577359, 2012). "IL-17RA−/− mice infected with C. neoformans strain H99γ survived the primary infection as well as a secondary challenge with wild-type cryptococci." (PMID 21359196, 2011). "In response to infection with Candida albicans, IL-17A, IL-17F and IL-17RA were up-regulated in mucosal tissues." (PMID 22174673, 2011). "Furthermore, IL-17RA signaling in B cells during MHV68 infection supported the expansion of both B-1a and B-1b B cells in the spleen and peritoneal cavity." (PMID 41335125, 2025).
infection (continued). "The expression levels of interleukin 1 beta (IL-1β), IL-6, IL-8, IL-10, IL-17A, and the interleukin receptor IL-17RA were significantly increased after infection with Yb2 and cYb2ΔsspA and were much greater than those in the brains of control and Yb2ΔsspA-infected ducks at 24 and 48 hpi." (PMID 38594770, 2024). "Due to the lower infection rate of female mice, it was difficult to perform statistical analysis; therefore, in subsequent studies, we used H. pylori infected male mice to investigate the role of IL-17RA in cancer." (PMID 39588838, 2024). "In our mouse model, the early phase of the protective immune response against B. melitensis varies according to the organs: at 120 hours post-infection, an IL-17RA-dependent (Th17) response controls the infection in the lungs and an IFNγ-dependent (Th1) response controls the infection in the spleen." (PMID 39186777, 2024). "EGFR was more abundant than IL-17RA on the cell surface from day 6 to day 9 post infection." (PMID 37270623, 2023). "As previously reported, mice lacking IL17RA showed a susceptibility to S. aureus with initially delayed clearance but were able to fully clear the infection by day 21 post-infection." (PMID 37691956, 2023). "When compared to IL17RA KO mice, DKO mice develop more severe and extensive skin lesions and at a higher penetrance, indicating cooperation between Ets1 and IL17RA in regulating susceptibility to such infections." (PMID 37691956, 2023). "Following infection with K. pneumoniae, ablation of IL-17RA (interleukin-17 receptor A) in SCGB1A1 (secretoglobin family 1A member 1) expressing club cells significantly reduces CXCL5 levels, leading to reduced neutrophil recruitment and increased bacterial burden." (PMID 36829255, 2023). "However, by day 20 post-infection, the bioluminescent signal in depleted IL17RA KO mice began to increase." (PMID 37691956, 2023). "In our study, the presence of IL-17RA appears to be relevant to reduce the parasite load in the acute phase of infection in the lungs, and this control in the initial phase is essential to prevent a greater number of larvae from migrating to more susceptible organs, such as the brain." (PMID 35844540, 2022). "When analyzing the frequency of CD4+ cells, it was observed that IL-17RA-/- 0dpi mice showed an increase in the frequency of CD4 T lymphocytes compared to WT 0dpi and that after infection there was a reduction in the frequency of these cells in the BAL in IL-17RA-/- mice." (PMID 35844540, 2022). "To test whether IL-17RA is involved in maintaining the oral epithelial barrier after radiation, we harvested kidneys on day 4 following infection to determine tissue fungal burden." (PMID 35628751, 2022). "Nasal infection with virulent B. melitensis 16M minimally impacted brucellae colonization of the lungs and spleen 4 weeks post-infection of IL-17RA−/− and IL-23p19−/− mice, but did enable greater colonization of the lungs at 5 and 12 days post-infection of IL-17RA−/− mice." (PMID 36620020, 2022). "Mice lacking IL-17RA have insufficient recruitment of neutrophils into the tongue tissue during infection, partially contributing to the increased susceptibility of Il17ra−/− mice to OPC compared to WT mice." (PMID 35628751, 2022). "In the later course of infection, IL-17A (which shares the receptor IL-17RA with IL-17C) released from immune cells such as γδ T cell may compensate the loss of IL-17C-signaling in S. aureus-infected wounds." (PMID 34576717, 2021). "IL-17RA signaling facilitates de novo lytic infection and MHV68 reactivation." (PMID 33824206, 2021). "IL-17RA signaling facilitates infection of germinal center/activated B cells." (PMID 33824206, 2021). "γδ T-cells were increased two months after infection in IL-17RA-deficient mice, but not in IL-22- or double IL-17RA-IL-22-deficient mice, as compared to wild-type mice." (PMID 27853279, 2016).